TNFRSF19 (TNF receptor superfamily member 19)
Diseases named in the same sentence as TNFRSF19 in open-access papers (continued):
Sharing a sentence is not in itself a finding about the gene and the disease.
tumor (23 papers, 2012 to 2025). "Oncogenic markers GPC3, HMGA2, and TNFRSF19 are dramatically increased in the tumor section of HBL116." (PMID 39796711, 2024). "The expression of several race-associated genes was also dependent on the MED12 mutation status of the tumor, being higher (FRAT2, TNFRSF19, ACP7, IRS4, PLEKHG4B, KRT17, SLN, and ZNF703) or lower (CAV2) in the mutated specimens compared with wild-type tumors." (PMID 37686244, 2023). "The TNFRSF19 expression levels were inversely correlated with the tumor staging, with significantly high expression in the tumors at stage I and low expression in the tumors at stages II/III/V." (PMID 31126313, 2019). "The Tcf1−/− tumor samples were clearly distinguished by factors involved in the Wnt-signaling pathway, Axin2, Lef1, and Tnfrsf19, or in the Notch signaling pathway, Deltex1 and Hes1." (PMID 23185135, 2012). "Probably, whether TNFRSF19 functions as an oncogene or a tumor suppressor may depend on when and where it is expressed." (PMID 31126313, 2019). "In contrast, BAMBI and TNFRSF19 positive cells from primary tumor sections did not express or only minimally expressed MKI67." (PMID 33898197, 2021). "The tumor suppressor function of TNFRSF19 observed in the present study is not consistent with the previously published papers." (PMID 31126313, 2019).
cancer (16 papers, 2014 to 2024). A tumor composed of atypical neoplastic, often pleomorphic cells that invade other tissues. "High expression of TNFRSF19 is associated with poor prognosis in various types of cancer." (PMID 34993138, 2021). "In addition, Tnfrsf19 mRNA belongs to the tumor necrosis factor receptor superfamily, which commonly transduces cytokine signals and is associated with poor prognosis in various types of cancer." (PMID 35127549, 2021). "TNF family members (TFMs) play a crucial role in different types of cancers, with TNF Receptor Superfamily Member 19 (TNFRSF19) standing out as a particularly important member in this category." (PMID 38560169, 2024). "We assessed the potential clinical impacts of deregulation of the TNFRSF19 expression first by real-time PCR analysis to compare the TNFRSF19 expression levels in 117 cancer tissues and their para-cancer tissues." (PMID 31126313, 2019). "TNFRSF19 belongs to the tumor necrosis factor (TNF) receptor superfamily and it has been identified that the up-regulation of TNFRSF19 is associated with poor outcomes in various types of cancer 45-47." (PMID 33437203, 2021).
TNFRSF19 also shares sentences with these, for which no sentence is quoted: prostate carcinoma (3 papers); gastric cancer (2); infection (2); alopecia (1); breast carcinoma (1); cerebral infarction (1); colorectal tumor (1); diabetes (1); head and neck squamous cell carcinoma (1); hepatoblastoma (1); Insulin resistance (1); intracranial aneurysms (1); multinodular goiter (1); multiple sclerosis (1); myeloproliferative neoplasm (1); prediabetes (1); scalded-skin syndrome (1); skin carcinoma (1); tuberous sclerosis syndrome (1); vascular malformation (1).